DMC1 (DNA meiotic recombinase 1)
Diseases named in the same sentence as DMC1 in open-access papers:
DMC1 is named in the same sentence as 34 diseases in open-access papers, as found by Europe PMC text mining. Sharing a sentence is not in itself a finding about the gene and the disease. The quoted sentences say what the papers report.
Infertility (6 papers, 2018 to 2024). "Cholesterol‐amino‐phosphate lipid nanoparticles (CAP LNPs) are developed to deliver mRNA and self‐amplifying RNA (saRNA) encoding Dmc1 protein to spermatocytes of Dmc1−/− infertile mice." (PMID 36748274, 2023). "DMC1 is a meiotic gene that has been associated with infertility in humans and mice but to our knowledge, the mechanism behind this infertility has yet to be linked to any system dysfunctions." (PMID 36566278, 2022). "For instance, a previous study demonstrated that a mouse knock-in model of DMC1 M200V, harbouring a human infertility allele of the meiotic recombinase DMC1, did not affect fertility in mice." (PMID 38540391, 2024). "In a mouse infertility model, we showed that by using the newly developed CAP LNPs to deliver the saRNA encoding the Dmc1 protein, the functional protein was restored and infertility of the Dmc1−/− mouse model was rescued consequently." (PMID 36748274, 2023). "The BRCA2-MEILB2-BRME1 complex is required for the assembly of RAD51 and DMC1 at meiotic DSBs during spermatogenesis since deletion of any component in the complex diminishes RAD51 and DMC1 foci formation at recombination sites, causing impaired DSB repair and infertility." (PMID 34440403, 2021). "However, they are infertile and show a severe block in meiotic progression associated with reduced RAD51 and DMC1 focus formation." (PMID 30305635, 2018). "However, deletion of exons 12-14 led to infertility with failure of DMC1 foci formation." (PMID 39333100, 2024). "Spermatocytes from infertile mice show decreased RAD51 focus formation, although DMC1 was not examined." (PMID 30305635, 2018).
male infertility (5 papers, 2020 to 2026). The inability of the male to effect fertilization of an ovum after a specified period of unprotected intercourse. "Gene DMC1 plays a vital role in repairing DNA double-strand breaks, and disruption of this repair process is linked to male infertility." (PMID 35711794, 2022). "The results demonstrate that CAP‐derived lipid nanoparticles (CAP LNPs) can deliver RNA including traditional mRNA and self‐amplifying RNA (saRNA) encoding DNA Meiotic Recombinase 1 (Dmc1) protein in spermatocytes and treat male infertility caused by the Dmc1 gene mutation." (PMID 36748274, 2023). "The accumulation of R-loops induced by the deletion of Rnaseh1 caused transcriptional dysfunction of meiotic genes and impaired meiotic recombination by altering the recruitment of RAD51 and DMC1, resulting in male infertility." (PMID 38858601, 2024). "Knockout of Meiok21 decreases the numbers of HSF2BP and DMC1/RAD51 foci, disrupting DSB repair, synapsis and crossover recombination and finally causing male infertility." (PMID 32463460, 2020).
Azoospermia (4 papers, 2022 to 2025). Absence of any measurable level of sperm,whereby spermatozoa cannot be observed even after centrifugation of the semen pellet. "Therefore, restoration of spermatogenesis in Dmc1−/− mice has strong clinical implications for the treatment of human azoospermia characterized by meiotic arrest." (PMID 36748274, 2023). "Interestingly, AFF1 has been linked to heifer conception rate in U.S. Holsteins, whereas DMC1 frameshift mutation causes nonobstructive azoospermia in humans." (PMID 40240941, 2025).
glioma (4 papers, 2015 to 2022). A benign or malignant brain and spinal cord tumor that arises from glial cells (astrocytes, oligodendrocytes, ependymal cells). "A few years later, another study investigated the aberrant activity of DMC1 in glioma and showed that loss of DMC1 inhibited the activation of the DNA damage response and increased radiosensitivity." (PMID 35251135, 2022). "Research on gliomas also shows that the loss of DMC1 can inhibit tumor cell growth in mice and prolong their survival." (PMID 33747079, 2021). "In this study, we investigated the aberrant activity of meiotic HR regulators in glioma, focusing on the meiosis-specific DMC1." (PMID 25906155, 2015). "Overall, the mRNA levels of ACVR1, STAT3, WNT5A, KLF4 and DMC1 were obviously decreased in glioma samples with 1p19q codeletion compared to those in glioma samples without 1p19q codeletion." (PMID 36435765, 2022). "In addition, DMC1-depleted GBM cells have larger nuclei consistent with an increase in aneuploidy, further supporting a critical and specific role of DMC1 in glioma cell responses to genotoxic stress." (PMID 25906155, 2015).
lymphoma (4 papers, 2006 to 2022). A malignant (clonal) proliferation of B- lymphocytes or T- lymphocytes which involves the lymph nodes, bone marrow and/or extranodal sites. "Key features of meiotic divisions with the meiotic cohesin REC8 linking sister centromeres, the meiotic recombinase DMC1 colocalising with DSB/γH2AX foci, and the omission of S-phase before mitosis were found in some polyploid lymphoma and HeLa cells induced after irradiation." (PMID 24025698, 2013).
ovarian carcinoma (4 papers, 2019 to 2022). A malignant neoplasm originating from the surface ovarian epithelium. "The results showed that high expression of XPC and RECQL and low expression of DMC1 were associated with poor prognosis in ovarian cancer patients." (PMID 31572446, 2019). "And the expression levels of TMPRSS3, DMC1, and HLA-DO in ovarian cancer tissue are significantly lower than those in normal ovarian tissue." (PMID 36081667, 2022). "On the other hand, low expression of DMC1 has been reported as a poor prognostic marker of ovarian cancer, together with high expression of XPC and RECQL." (PMID 33202377, 2020). "In addition, studies have shown that DMC1 expression in ovarian cancer stem cells may enhance the ability of cancer stem cells to repair DNA, leading to resistance to PARP inhibitors." (PMID 33747079, 2021). "More importantly, DMC1 interacts directly with the DNA repair gene BRCA2, which may provide possibilities for synthetic lethality targets for ovarian cancer." (PMID 31572446, 2019).
cervical cancer (3 papers, 2013 to 2021). A primary or metastatic malignant neoplasm involving the cervix. "Loss of DMC1 expression is found in multiple human cancers, and SNPs for DMC1 are associated with cervical cancer." (PMID 31572446, 2019). "In addition, ectopic expression of some key meiotic genes was also reported in primary tumours, for example MOS in NSCLC, DMC1 in cervical cancer, SPO11, REC8, SGO1 and HORMAD1 in melanoma." (PMID 24025698, 2013).
endometrial cancer (2 papers, 2021 to 2025). Primary or metastatic malignant neoplasm involving the endometrium (mucous membrane that lines the endometrial cavity). "Among them, CD3EAP and LY6H are prognostic risk genes for patients with endometrial cancer (HR > 1), while DMC1 and TLE2 are prognostic protective genes (HR < 1)." (PMID 33747079, 2021). "In addition, the DMC1 gene was used in the construction of the radiosensitivity index (RSI) to assess the sensitivity and prognosis of radiotherapy, especially in endometrial cancer providing an important perspective on the DNA damage repair process." (PMID 40530955, 2025).
fertility disorders (2 papers, 2019). "While Meilb2 KO male mice showed almost complete loss of RAD51 and DMC1 localizations leading to complete sterility, the female KO mice showed a reduction by almost half in the localization of these recombinases leading to subfertility (a 40% reduction in litter size)." (PMID 30760716, 2019). "The first observed phenotypic feature of all the identified dmc1 mutants selected for the cytological analysis was partial sterility of their spikes, which indicated some fertility disorders." (PMID 31244877, 2019). "We show here that MEILB2 is a master regulator of meiotic recombinases and the localization of RAD51 and DMC1 at meiotic DSBs is completely abolished in Meilb2 KO male mice, leading to errors in meiotic DSB repair and subsequent sterility." (PMID 30760716, 2019). "This suggests that fertility disorders are a common feature of individuals lacking the DMC1 gene in different species." (PMID 31244877, 2019).
premature ovarian failure (2 papers, 2019 to 2024). "DMC1 deficiency leads to the abnormal formation of synaptic complex and the disordered separation of homologous chromosomes, and the deletion or mutation of Dmc1 in human and mice can lead to spermatogenesis disorder and premature ovarian failure." (PMID 31520246, 2019).
amoebiasis (1 paper, 2015). "Previous work shows Dmc1 is expressed in Entamoeba histolytica, a eukaryotic parasite responsible for amoebiasis throughout the world, suggesting this organism undergoes meiosis." (PMID 26422142, 2015).
cyst (1 paper, 2024). A sac-like closed membranous structure that may be empty or contain fluid or amorphous material. "RAD21, SMC3, and MEI2 are linked to bloom-promoting sex, HOP2 and MSH4 to cyst germination, while SPO11, MND1, and DMC1 are common to both cyst-forming and non-encysting sex." (PMID 39367346, 2024).
glioblastoma (1 paper, 2019). The most malignant astrocytic tumor (WHO grade IV). "In this regard, it is interesting to note that mis-expression of Dmc1 in mitotic cells is encountered in human glioblastoma cell lines and accompanied by heightened replication stress." (PMID 30916344, 2019).
lymphoid tumours (1 paper, 2006).
malaria (1 paper, 2012). Malaria is a serious and sometimes fatal disease caused by a parasite that commonly infects a certain type of mosquito which feeds on humans. "In this report we applied reverse genetics to examine the role of Dmc1 in P. berghei, a rodent malaria parasite." (PMID 23285059, 2012). "Dmc1 has homologues in the human (P. vivax), non-human primate (P. knowlesi) and rodent (P.yoelii, P. chabaudi) malaria parasites." (PMID 23285059, 2012).
nasopharyngeal carcinoma (1 paper, 2025). A carcinoma arising from the nasopharyngeal epithelium. "Furthermore, we found that the core genes of the nasopharyngeal carcinoma radiosensitivity signature (NPC-RSS), namely SMARCA2, DMC1, CD9, PSG4, and KNG1, had significant correlations with previously published genes related to radiosensitization." (PMID 40530955, 2025).
ovarian dysgenesis (1 paper, 2015). "Importantly, mutations introduced into these Hop2 and Mnd1 domains, including the HOP2 p.del201Glu mutation present in a patient of XX ovarian dysgenesis, diminish the association and functional synergy of Hop2-Mnd1 with both RAD51 and DMC1." (PMID 25820426, 2015).
ovarian failure (1 paper, 2010). "In contrast to other critical genes during meiosis, such as Dmc1, Msh5, Spo11 and Atm that cause early ovarian failure due to rapid loss of oocytes following disruption of meiosis I, Hormad1 deficiency does not activate apoptotic pathways and does not lead to gross premature loss of oocytes." (PMID 21079677, 2010).
sarcoma (1 paper, 2023). A usually aggressive malignant neoplasm of the soft tissue or bone. "MDM2 and DMC1 were significantly downregulated in HRDhigh sarcoma, but showed a sarcoma histotype‐specific expression." (PMID 36779660, 2023).
Sézary Syndrome (1 paper, 2019). "Our results show significant differential gene expression of STAG3, SGO2, SYCP3, and DMC1 in a cohort of Sézary Syndrome patients when compared to healthy controls." (PMID 31214493, 2019).
viral infection (1 paper, 2010). "In this population-based study, we found nine genes/regions associated with CIN3/cancer, 6 of which remained significant at a FDR≤0.2 – three DNA repair genes (GTF2H4, DUT, and DMC1) and three viral infection and cell entry related genes (OAS3, SULF1, and IFNG)." (PMID 20084279, 2010).
cancer (16 papers, 2006 to 2025). A tumor composed of atypical neoplastic, often pleomorphic cells that invade other tissues. "DMC1, short for “downregulated in multiple cancers-1,” plays an important role in DNA binding and repairing, with loss expression identified in multiple human cancers." (PMID 35480120, 2022). "DMC1’s aberrant expression in cancer cells contributes to proliferation and recovery from genotoxic stress by mimicking HR mechanisms, thus aiding in maintaining genomic stability under therapeutic stress." (PMID 40918650, 2025). "In a study of radiation-induced mitotic catastrophe in various cancer cell lines, genes specifically associated with meiosis were shown to be upregulated (i.e., SCP3, REC8 and DMC1)." (PMID 27275820, 2016). "Proteins involved in repairing the DSB generated during meiosis, such as Testis Expressed 15 (TEX15) and Disrupted Meiotic cDNA1 (DMC1), are also expressed in cancer." (PMID 27275820, 2016). "Our studies are the first to establish a functional role, beyond expression, of DMC1 in cancer cells." (PMID 25906155, 2015). "From each region, the single most significant SNPs associated with CIN3/cancer were OAS3 rs12302655, SULF1 rs4737999, IFNG rs11177074, DUT rs3784621, DMC1 rs5757133, GTF2H4 rs2894054, EVER1/EVER2 rs9893818 (p-trends≤0.001)." (PMID 20084279, 2010). "Similarly to other genes involved in meiotic recombination, DMC1 was found to be ectopically expressed in various cancer cell lines including cervical, colon, breast, glioblastoma and lymphoma cancer cell lines as well as in CTCL biopsy samples." (PMID 35251135, 2022). "Interestingly, the upregulation of DMC1 was reported in a number of studies to drive the resistance of cancer cells to various cytotoxic and genotoxic agents." (PMID 35251135, 2022). "However, there are instances of meiotic genes, including Dmc1, being aberrantly upregulated in cancer cells in response to radiation-induced MC." (PMID 26422142, 2015). "Although there is no data specifically implicating these pathways in cancer, it is important to note that SPO11, DMC1, and HORMAD1 have all been shown to be increased in cancer." (PMID 23840955, 2013). "Among them, three genes (DMC1, PENK, and SIM2) were selected for further independent validation with additional normal tissues and BCa tissues because the genes showed higher methylation levels in all cancer tissues than in normal tissues." (PMID 36403035, 2022). "Furthermore, the identified hub genes of the individual GRNs, e.g., HID1/DMC1 (tumor development), RNF17/TDRD4 (cancer antigen) and CYP4A11 (angiogenesis/ metastasis) are known cancer associated markers." (PMID 25971253, 2015). "Other genes, including DMC1, STAG3 and REC8, allow somatic cancer cells to escape radiation-induced cell death without directly affecting the intracellular DNA repair pathways." (PMID 35251135, 2022).
tumor (7 papers, 2011 to 2025). "Furthermore, loss of DMC1 reduced tumor growth and prolonged survival in vivo." (PMID 25906155, 2015). "Previous studies have demonstrated that the core genes of NPC-RSS, including SMARCA2, DMC1, CD9, PSG4, and KNG1, are associated with tumor radiosensitization to varying degrees." (PMID 40530955, 2025). "Targeting DMC1 significantly extended the lifespan of tumor-bearing hosts relative to control animals, with a median survival of 37 days in the shControl arm and 62 and 83 days in the shDMC1.1068 and shDMC1.826 arms, respectively." (PMID 25906155, 2015). "The human ortholog of Ftp105 is C17orf28/DMC1 (down-regulated in multiple cancers), a potential tumor suppressor." (PMID 21760946, 2011). "Although limitations in radiotolerance of the immunocompromised mouse model used in our studies prevented in vivo studies of combined DMC1 depletion and IR, we found delayed tumor progression and increased survival with DMC1 depletion supports the therapeutic potential of DMC1 targeting." (PMID 25906155, 2015).
infection (2 papers, 2012 to 2019). The state of being infected such as from the introduction of a foreign agent such as serum, vaccine, antigenic substance or organism. "The timing of protein expression was similar to that of mRNA expression, with DMC1 positive parasites first detected at 42 h post-infection, peaking at 72 h post-infection and then decreasing in number." (PMID 31015448, 2019). "DMC1 gene expression was first detected at 42 h post-infection, i.e., the same time gamonts were first seen by TEM." (PMID 31015448, 2019). "A clear subset of parasite vacuoles stained positive for DMC1 at 72 h post-infection, confirming antibody specificity." (PMID 31015448, 2019). "Interestingly, DMC1 expression decreased after peaking at 72 h post-infection." (PMID 31015448, 2019). "The lack of infection could be due to defects in sporozoites formation as a result of Dmc1 disruption or that the sporozoite density failed to reach a critical threshold at any given point required for a productive infection in mice." (PMID 23285059, 2012).
DMC1 also shares sentences with these, for which no sentence is quoted: colon cancer (2 papers); Fanconi anemia (2); amenorrhea (1); bladder tumors (1); cutaneous melanoma (1); epilepsy (1); female sterility (1); melanoma (1); non-small cell lung carcinoma (1); Premature ovarian insufficiency (1).